RN7SL684P (RNA, 7SL, cytoplasmic 684, pseudogene)
Gene: Miscellaneous RNA gene on chromosome 5 (176,547,433 to 176,547,726, reverse strand). Ensembl gene ENSG00000243959.
Homologues: Orthologues: chimpanzee Metazoa_SRP (95% identical), macaque Metazoa_SRP (90% identical), dog Metazoa_SRP (56% identical). Paralogues in human: RN7SL1 (80% identical), RN7SL2 (79% identical), RN7SL3 (79% identical), RN7SL664P (78% identical), RN7SL408P (77% identical), RN7SL296P (77% identical), RN7SL431P (77% identical), RN7SL448P (77% identical), RN7SL507P (77% identical), RN7SL597P (77% identical), RN7SL480P (76% identical), RN7SL50P (76% identical), and 702 more.